CD226 (CD226 molecule)
Diseases named in the same sentence as CD226 in open-access papers (continued):
Sharing a sentence is not in itself a finding about the gene and the disease.
tumor (continued). "The association between the percentages of CD8+CD226+T cells/CD8+T cells, CD8+CD226+T cells/CD8+T cells in the epithelial cell region, and CD8+CD226+T cells/CD8+T cells in the stromal cell region in tumor and clinical features of GC patients." (PMID 37056782, 2023). "The overall abundance of CD226 + TIGIT+ co-expressing cells was low (<8% mean frequency) for each T cell subset within the tumour." (PMID 37596248, 2023). "As a co-stimulatory receptor that mediates T cell adhesion and execution of cytotoxicity, CD226 competes with immune checkpoints like TIGIT for the same ligands expressed by cancer cells to execute the anti-tumor effects." (PMID 37398674, 2023). "As CD226 is involved in tumour growth control, the inhibition of miR-150-5p leads to the activation of cytotoxic NK cells through the functioning of CD226." (PMID 38203731, 2023). "The greatest co-expression of TIGIT and CD226 was observed within a small portion of c8, which was more abundant in the blood than the tumour (dashed line on top row)." (PMID 37596248, 2023). "These vesicles have a significant impact on the tumour microenvironment by inducing immunosuppressive conditions and reducing CD226 expression on NK cells." (PMID 38203731, 2023). "RNA-seq data from TCGA STAD were downloaded, and the relationship between CD226 and tumor purity, stromal and immune score, as well as with signature genes of the specific cells and T cell activation effectors in TME, were analyzed." (PMID 37056782, 2023). "CD96 co-expression with CD226 was also significantly more frequent in cells from the blood than from the tumour (>3-fold mean difference in all subsets) and rare in tumours (Highest mean frequency of 7.3% ±1.4% in non-Treg CD4 + T cells)." (PMID 37596248, 2023). "Tumor-infiltrating CD8+ T cells expressing high levels of CD226, previously known as DNAX accessory molecule-1 (DNAM-1), possess greater self-renewal capacity and responsiveness." (PMID 37626933, 2023). "Several reports have also shown that CD226 signaling in CD8+T cells plays a vital role in the anti-tumor response in the mouse tumor model." (PMID 37056782, 2023). "We also found that the frequencies of total CD8+CD226+TILs, CD8+CD226+TILs in epithelial cell region and CD8+CD226+TILs in stromal cell region were significantly associated with tumor size (P=0.022, P=0.0495, P=0.041, respectively)." (PMID 37056782, 2023). "Our findings provided insights into the interaction pattern between co-stimulatory receptor CD226 and tumor cells as well as the infiltrating immune cells in the TME in GC." (PMID 37056782, 2023). "The association between the percentages of CD8+CD226+T cells, CD8+CD226+T cells in the epithelial cell region, and CD8+CD226+T cells in the stromal cell region in tumor and clinical features of GC patients." (PMID 37056782, 2023). "Taken together, these data suggest TIGIT and CD226 co-expression is rare on immune cells within the tumour microenvironment and that CD155 is abundant on mAPCs for TIGIT-expressing T and NK cells to engage." (PMID 37596248, 2023). "IL-15 can up-regulate TIGIT and CD226 via tumor-infiltrating NK cells, increasing NK cell-mediated cytotoxicity and reducing tumor metastases." (PMID 37494663, 2023). "In contrast, TIGIT and CD96 are inhibitory receptors, and PVR upregulation in heterogeneous tumor cells results in tumor cell recognition and binding by activating receptor CD226 and the inhibitory receptors TIGIT and CD96." (PMID 35625835, 2022). "CD226 is an activating receptor upon which multiple checkpoint inhibitor pathways converge, and thus is likely to be critical in generating optimal anti-tumor CD8+ T cell responses." (PMID 35263569, 2022). "It has been reported that CD155, widely expressed in human and mouse tumor-infiltrating myeloid cells, promotes tumor cell growth and metastasis by down-regulating the expression of CD226 and inhibiting the effects of CD8+T and NK cells." (PMID 35433470, 2022).
tumor (continued). "The importance of CD226 in regulating anti-tumor responses is demonstrated in mouse tumor models where use of a CD226-neutralizing monoclonal antibody (mAb) abrogates the efficacy of combining mAbs against PD-L1 and TIGIT." (PMID 35263569, 2022). "Based on this, and our observation that CD226 is readily expressed on neoantigen-specific T cells after vaccination, we treated tumor-bearing mice with combination PD-1/TIGIT blockade and neoantigen vaccine." (PMID 36569934, 2022). "In contrast to delayed tumor progression in TIGIT-/- and CD96-/-, CD226-deficient mice exhibit increased susceptibility to MCA-induced fibrosarcomas as well as metastatic lung colonization (e.g., LLC lung and RM-1 prostate tumors)." (PMID 35812451, 2022). "The combination therapy of the TIGIT mAb and CD226 agonist further activated NK cells and produced a greater anti-tumor response." (PMID 36303184, 2022). "Upon the inhibition of the ubiquitin pathway, increased Nectin2 surface expression renders tumor cells more efficiently recognized and lysed by NK cells by mediating the CD226-dependent co-stimulation of both NK and CD8+ T cells." (PMID 36553083, 2022). "In 2018, Zhigang Tian lab found that the blockade of TIGIT reversed the exhaustion of tumor-infiltrating NK cells, increased the frequency of tumor-infiltrating NK cells expressing CD107a, tumor necrosis factor, interferon-γ, and CD226." (PMID 36289396, 2022). "To understand this relationship in greater detail, we monitored the growth of syngeneic CT26 tumor cells in wild-type (WT) or Cd226−/− mice." (PMID 35263569, 2022). "For example, in non-small cell lung cancer (NSCLC), CD226 expression is reduced on tumor-infiltrating NK cells relative to cells from normal adjacent tissues (NAT) and peripheral blood." (PMID 35812451, 2022). "This TIGIT targeting approach will have two benefits - one on tumor cells and the other on cytotoxic immune cells - allowing CD226 to bind to CD155 to reactivate T cells and NK cells for anti-tumor cytotoxic killing." (PMID 36163179, 2022). "Further emphasizing the potential interaction among diverse costimulatory and inhibitory pathways are observations from preclinical studies demonstrating that efficacy of anti-CD137, anti-GITR, and anti-CTLA-4 required CD226 for anti-tumor activity." (PMID 35263569, 2022). "For example, PVR overexpression in tumor cells increases the activation of immune cells and tumor cell death through interaction with CD226." (PMID 35625835, 2022). "It is unclear if this is a direct or indirect effect, however, TGF-β-dependent modulation of CD226 has the potential to skew axis signaling in the tumor microenvironment (TME), enhancing the potential for immune evasion." (PMID 35812451, 2022). "Among those proteins, we next focused on CD226, because soluble recombinant CD226 and also CD226 on NK-EVs have cytolytic activity against tumor cells." (PMID 34316033, 2022). "These exosomes are captured by tumor cells through macropinocytosis, and blocking CD226 (using monoclonal antibodies) reduces the cytolytic activity of activated NK cells exosomes and EVs." (PMID 35550636, 2022). "In contrast, depletion of Bcl9 in CT26 tumor cells increased CD226+CD8+ T cell tumor infiltration accompanied by increased expression of Pvr/CD155." (PMID 34417435, 2021). "Inhibition of miR-150 improved tumor surveillance by reversing CD226 expression and subsequently reinstating cytotoxic NK cell activity." (PMID 34944871, 2021). "Nonetheless, efficient tumor cell killing requires additional activating signaling, such as that of DNAM-1 (CD226) interacting Nectin-2 (CD112) and poliovirus receptor (PVR or CD155) ligands." (PMID 34064810, 2021). "DNAM-1 (CD226) is another important NK cell receptor that mediates anti-tumor immunity 62; it is also important for NK cells to discriminate viruses." (PMID 34400893, 2021).
tumor (continued). "NECL5 interacts with CD226 on the platelet surface, enabling tumor cell adhesion to the endothelial vasculature, thereby leading to tumor metastasis." (PMID 34322381, 2021). "Remarkably, CD226 is also required for enhancement of anti-tumor CD8+ T-cells responses by PD-1 blockade." (PMID 34367161, 2021). "CD155 on antigen-presenting cells or tumor cells binds to CD226 on T cells and NK cells, which is similar to the interaction between PD-1 and PD-L119,29." (PMID 33469055, 2021). "The co-inhibitory receptors CD96, TIGIT, PVRIG and the costimulatory receptor CD226 comprise a critical regulatory system for lymphocyte activity and anti-tumor immunity, and they share the same ligands CD155 and PVRL2." (PMID 34174928, 2021). "PVRL2 (CD112), known as the ligand of PVRIG and CD226, is overexpressed in different types of tumor cell and plays an immunosuppressive role in T cell function." (PMID 33747255, 2021). "The importance of the CD226–PVR axis in regulating tumor immunity has been shown in vitro and in vivo in preclinical mouse models." (PMID 33670993, 2021). "CD155-/- mice displayed reduced tumor growth and metastasis via CD226 upregulation and enhanced effector functions of NK cells." (PMID 34367161, 2021). "The effect of inhibiting the CD226–PVR axis on anti-tumor immune responses was investigated using anti-CD226 blocking mAbs." (PMID 33670993, 2021). "When combined with its ligand CD115 or CD112 upregulated in tumor cells, CD226 facilitates the cytotoxicity of NK cells." (PMID 33549054, 2021). "Mechanistically, tumor cells expressing CD155 impair NK cell functions by downregulating their CD226 expression." (PMID 34367161, 2021). "Anti-TIGIT antibody mediates the rescue of anti-tumor responses of effector T cells that requires the costimulatory signal of CD226." (PMID 34174928, 2021). "Accumulating evidence has shown that CD226 plays a pivotal role in tumor recognition and cancer immune surveillance, even promoting antitumor immune responses mediated by NK and T cells." (PMID 33549054, 2021). "In BRCA, the expression of PVRL1/CD111, PVRL2/CD112, TIGIT, and DNAM-1/CD226 in tumor tissues was significantly higher than that in normal tissues, but PVRL3/CD113 showed an opposite expression pattern." (PMID 33581644, 2021). "The level of CD155 was significantly higher in tumor cells than in adjacent tissues, pointing towards the potential of therapies that increase CD226 expression on NK cells." (PMID 33321719, 2020). "Formation of stable conjugates with tumor cells is essential for NK cells to exert tumor killing effects, and CD226 enables prolonged stable interaction between NK and tumor cells." (PMID 32850777, 2020). "The receptors on NK membranes, especially activated receptors such as NKp30, NKp44 NKp46, DNAM-1 (CD226), and NKG2D, are closely associated with tumor recognition and tumor killing." (PMID 33396603, 2020). "Recently, the CD226/TIGIT axis has been identified as an important regulator in anti-tumor and anti-viral T cell responses." (PMID 32983106, 2020). "Nevertheless, NK cells exert DNAM-1 (CD226)-mediated tumor recognition if the tumor cell expresses DNAM-1 ligands to overcome the NKG2D blockade." (PMID 32499786, 2020). "An activating receptor DNAM-1 (CD226) on cytotoxic lymphocytes plays a critical role for recognition and elimination of tumor cells by recognition of its ligand CD155 and CD112." (PMID 32787882, 2020). "In particular, CD155 once up-regulated on different types of tumor cells is recognized by a group of receptors expressed on T and NK cells: The activating receptor DNAM-1 (CD226) and the inhibitory receptors TIGIT and TACTILE (CD96)." (PMID 32019260, 2020). "There is a paradoxical increase in CD226 with platelet cloaked tumour cells, an artefact from CD226+ activated platelets sticking to NK cells." (PMID 30908480, 2019). "T cell Ig and ITIM domain receptor and CD226 were expressed in the lymphocytes near the tumour tissue and the adjacent tissues." (PMID 31090213, 2019).
tumor (continued). "CD226 was inhibited when incubated with uncloaked tumour cells alone, a phenomenon that has been published previously." (PMID 30908480, 2019). "We have demonstrated that platelets robustly suppress surface expression of CD226 and CD96 on the NK cell surface and their associated ligands on the tumour cell to further enhance NK cell suppression." (PMID 30908480, 2019). "TIGIT and CD226 expression in various tumor types and normal tissues was derived from TCGA (The Cancer Genome Atlas), GTEX (Genotype-Tissue Expression Project), and immunohistochemistry." (PMID 30400822, 2018). "Overexpressing CD2 and CD226 on our T cell reporters greatly increased their sensitivity to tumor cells presenting their cognate antigens." (PMID 29707134, 2018). "CD226 is an activating receptor that is important for NK cell-mediated tumor surveillance and ligand binding increases the cytotoxic potential of NK cells against target cells." (PMID 27148271, 2016). "Emerging evidence suggests that DNAM-1 (CD226) play an important role in the recognition of tumor cells and their lysis by cytotoxic T lymphocytes (CTL) and NK cells." (PMID 27049654, 2016). "The tumor sample was divided into groups according to tumor characteristics known to be indicators of cancer progression, and the percentage of CD226+ and CD96+ NK cells was compared between these groups." (PMID 27626490, 2016). "Although CD155 present on tumor cells can induce CD226-dependent immunosurveillance, the expression of CD96 and TIGIT on the same cell can counterbalance CD226 activity." (PMID 27148271, 2016). "In human NK cells, DNAM-1 (CD226) functions primarily as an activating receptor involved in killing of different tumour targets and in NK-DC crosstalk." (PMID 26436997, 2015). "CD112 (Nectin-2, PVRL2) and CD155 (Necl5, PVR) bind CD226 (DNAM-1), which potentiates in vitro the cytotoxicity of NK cells against a wide range of tumor cells; CD58 (LFA-3) binds CD2 and its co-engagement with ICAM-1 increases NK response." (PMID 26106390, 2015). "Based on that, CD226 is thought to be one of the major activating NK receptors and involved in tumor immunosurveillance." (PMID 19490613, 2009). "On the other hand, the interaction between TIGIT and CD226 attenuates immune operations, while nectin-2 and nectin-4 are identified as promising targets in cancer treatment due to their effects on the behavior of tumor cells." (PMID 40777027, 2025). "Finally, our findings highlight the potential role of RUNX2 in CD8+CD226+ T cell effector functions positively correlated with tumor‐infiltrating CD8+ T cells." (PMID 39777847, 2025). "CD226 is an activating receptor, and its expression on TILs might enhance the anti-tumor ability of TILs, whereas its expression on TC contributes to the immune escape ability of TC." (PMID 41181119, 2025). "Similarly, CD226 expression on CD8+ tumor-infiltrating lymphocytes from colorectal cancer liver metastases serves as an independent prognostic factor, associated with better survival outcomes." (PMID 40723878, 2025). "Additionally, DNAM-1 (CD226) is an activating receptor on cytotoxic lymphocytes that promotes tumor-cell recognition and elimination by binding to ligands CD155 and CD112." (PMID 40723175, 2025). "Emerging preclinical evidence positions CD226 activation as a pivotal amplifier of anti-tumor immunity, synergizing with chemotherapy, immune checkpoint blockade, and vaccine strategies to enhance NK/cytotoxic T lymphocyte (CTL) cytotoxicity across diverse malignancies." (PMID 40723878, 2025). "CD226 plays a vital role in NK cell cytotoxicity, interacting with its ligands on tumor targets." (PMID 40624674, 2025). "Moreover, soluble CD226 exhibit cytotoxic activity against CD155-expressing tumor cells, suggesting its potential as a biotherapeutic agent." (PMID 40723878, 2025).
tumor (continued). "However, this balance can be disrupted within the tumor microenvironment, where inhibitory signaling predominates due to decreased CD226 and increased TIGIT expression." (PMID 40411696, 2025). "Future research should focus on unravelling mechanisms of primary and adaptive resistance, optimizing combination regimens, and stratifying patients based on CD226 expression, PD-L1 levels, and tumor immune contexture to fully harness the therapeutic potential of TIGIT inhibition." (PMID 41303538, 2025). "Furthermore, co-blocking TIGIT and PD-1 not only relieves the inhibition of CD226 by PD-1 but also restores CD226 functionality, significantly enhancing the anti-tumor response of immune cells." (PMID 41473772, 2025). "When CD226 on CD8+ T cells attaches to CD155 on tumor cells, CD226 is degraded." (PMID 39223632, 2024). "This disparity may be due to the heterogeneity of the population represented by CD226 downregulation or the varied status of T-cell differentiation depending on the tumor burden or variations in tumor types." (PMID 39349829, 2024). "Additionally, platelet-derived TGF-β further enhances tumour metastasis by inhibiting the expression of CD226 and CD96 on NK cell surface, protecting tumour cells from being recognised by NK cells." (PMID 39450176, 2024). "In contrast, killer cell lectin like receptor K1 (KLRK1; also known as NKG2D), CD226 molecule (CD226; also known as DNAM-1) and natural cytotoxicity triggering receptor 1 (NCR1; also known as NKp46) can bind to ligands on the tumour surface and activate NK cells, causing them to release cytotoxins." (PMID 39070147, 2024). "In line with a recent study of tumor-infiltrating T cells, these results also suggest that inhibiting CD226 signaling by TIGIT might be one of the major mechanisms by which TIGIT imparts its immune regulation in self-reactive T cells." (PMID 38533515, 2024). "Our findings also highlight the importance of IL15 use for CD226 expression and T cell functionality restoration and that this cytokine may be included in immunotherapeutic strategies to increase tumor control." (PMID 36717657, 2023). "Notably, the frequency of CD226 expression on TIGIT + T cells was >2-fold lower in cells from tumours compared to those from blood." (PMID 37596248, 2023). "In addition, CD8+T cells with reduced or missing expression of CD226 show dysfunction and are related to drug resistance of tumor immunotherapy." (PMID 37056782, 2023). "The Eomes-dependent loss of CD226 limits TCR signaling and anti-tumor effects." (PMID 37398674, 2023). "Indeed, even in CD226-deficient mice, TIGIT blockade was still able to dramatically reduce tumour burden in a murine cancer model, although mice were in general less able to control tumours." (PMID 37596248, 2023). "Based on the data from CD226-deficient mice, Gilfillan concluded that CD226 plays an indispensable role in triggering the activation of CD8+ T cells in peripheral tissues, whereas it augments the ability of NK cells to execute cytotoxicity against tumor cells." (PMID 37291608, 2023). "Furthermore, we provided insights into the interplay between co-stimulatory receptor CD226 and tumor cells as well as other infiltrating immune cells in the TME of GC." (PMID 37056782, 2023). "Notably, a recent study found that the intercellular communications between PVR+ malignant cells and CD226+ T cells can enhance the anti-tumor immune response." (PMID 37859818, 2023). "CD226 was negatively correlated with tumor purity and positively correlated with the immune score." (PMID 37056782, 2023). "It is well-known that CD226 serves as a critical activating receptor on various immune cells, such as lymphocytes and monocytes, and it is suggested to promote anti-tumor immunity in the tumor microenvironment (TME)." (PMID 37056782, 2023).